RN7SL269P (RNA, 7SL, cytoplasmic 269, pseudogene)
Gene: Miscellaneous RNA gene on chromosome 1 (169,957,942 to 169,958,246, reverse strand). Ensembl gene ENSG00000243051.
Homologues: Orthologues: chimpanzee Metazoa_SRP (99% identical), macaque Metazoa_SRP (94% identical). Paralogues in human: RN7SL2 (81% identical), RN7SL1 (80% identical), RN7SL3 (80% identical), RN7SL769P (79% identical), RN7SL45P (79% identical), RN7SL820P (79% identical), RN7SL88P (79% identical), RN7SL126P (78% identical), RN7SL444P (78% identical), RN7SL7P (78% identical), RN7SL326P (77% identical), RN7SL336P (77% identical), and 702 more.